RASSF10 (Ras association domain family member 10)
Diseases named in the same sentence as RASSF10 in open-access papers (continued):
Sharing a sentence is not in itself a finding about the gene and the disease.
leukemia (3 papers, 2009 to 2024). A malignant (clonal) hematologic disorder, involving hematopoietic stem cells and characterized by the presence of primitive or atypical myeloid or lymphoid cells in the bone marrow and the blood. "Nevertheless, inactivation of RASSF6 or RASSF10 by promoter DNA hypermethylation appears to be an event associated with the majority of childhood leukaemias." (PMID 19570220, 2009). "For instance, Hesson and collaborators have reported that RASSF6 and RASSF10, tumor suppressor genes of the Ras-association family (RASSF), are hypermethylated in leukemia cells." (PMID 39308891, 2024). "Epigenetic inactivation of RASSF6 and RASSF10 is an extremely frequent event in the pathogenesis of childhood leukemia." (PMID 26334503, 2015). "This study also warrants further investigation of the newly identified RASSF member RASSF10 and its potential role in leukaemia." (PMID 19570220, 2009). "COBRA and bisulphite sequencing revealed RASSF6 and RASSF10 were the only RASSF members with a high frequency of leukaemia-specific methylation." (PMID 19570220, 2009). "To investigate the effects of methylation on RASSF10 expression we analysed the leukaemia cell lines THP-1 and SUP-T1 using RT-PCR." (PMID 19570220, 2009). "Our data also suggests that of the newly identified 'N-terminal' RASSF genes, RASSF10 is an interesting candidate for further analysis in other types of cancer and for functional investigation to ascertain its role in leukaemias." (PMID 19570220, 2009). "The RASSF10 CpG island was heavily methylated in 7/7 leukaemia cell lines." (PMID 19570220, 2009). "Given the expression of RASSF10 in bone marrow we questioned whether RASSF10 is also inactivated by promoter methylation in the same series of childhood leukaemias." (PMID 19570220, 2009). "A summary of RASSF6 and RASSF10 promoter methylation in leukaemia and control samples." (PMID 19570220, 2009). "Interestingly, such epigenetic silencing of RASSF6 and RASSF10 appeared to be extremely frequent in childhood leukemia, and were reversed by treatment with the hypomethylating drug decitabine, underlying the potential of epigenetic drugs in the treatment of HMs." (PMID 39308891, 2024). "This study shows the hypermethylation profile of RASSF genes in leukaemias is distinct from that of solid tumours and represents the first report of inactivation of RASSF6 or RASSF10 in cancer." (PMID 19570220, 2009).
pancreas carcinoma (3 papers, 2019 to 2021). "JUND was also reported to regulate the progression of pancreatic cancer by activating the tumor suppressor gene RASSF10." (PMID 34290570, 2021). "In previous studies, we have shown that the RASSF10 promoter is methylated in patient tumors samples of the adrenal gland, head and neck, sarcoma, pancreas carcinoma, and Merkel cell carcinoma." (PMID 32047266, 2020). "Our present comprehensive work is the finalization of our previous research in smaller data sets in which we have shown that the promoter of RASSF10 is methylated in patient tumors samples of the adrenal gland, head and neck, sarcoma, pancreas carcinoma and Merkel cell carcinoma." (PMID 31817988, 2019).
sarcoma (3 papers, 2016 to 2020). A usually aggressive malignant neoplasm of the soft tissue or bone. "Interestingly, in our earlier findings in sarcoma we observed an increase in RASSF10 methylation with tumour stage." (PMID 26927176, 2016).
thyroid cancer (3 papers, 2012 to 2020). "RASSF10, located at 11p15.2, has recently been reported as methylated and silenced in childhood leukemia, thyroid cancer and in astrocytic glioma." (PMID 22695170, 2012).
acute lymphoblastic leukemia (2 papers, 2021 to 2022). Leukemia with an acute onset, characterized by the presence of lymphoblasts in the bone marrow and the peripheral blood. "For example, the presence of DNA hypermethylation of RASSF6 and RASSF10 always indicates a poor prognosis in acute lymphoblastic leukemia (ALL)." (PMID 35865472, 2022). "It was observed that the RASSF6 methylation was more frequent in B-Cell Acute Lymphoblastic Leukemia (B-ALL) cases compared with T-cell acute lymphoblastic leukaemia (T-ALL) cases, whereas the RASSF10 hyper methylation was more frequent in T-ALL compared with pre-B-ALL and B-ALL patients." (PMID 33883026, 2021).
cervical carcinoma (2 papers, 2016 to 2019). A carcinoma arising from either the exocervical squamous epithelium or the endocervical glandular epithelium. "The cervix carcinoma cell line HeLa, due to its strong RASSF10 methylation, and an in vitro methylated DNA were used as positive controls." (PMID 26927176, 2016).
colon carcinoma (2 papers, 2019 to 2021). "Similarly, RASSF10 expression was reduced in metastatic melanoma vs. non-metastatic melanoma types and in colon carcinoma vs. adenocarcinoma (respectively)." (PMID 31817988, 2019).
kidney cancer (2 papers, 2019 to 2020). Primary or metastatic malignant neoplasm involving the kidney. "We could clearly show that the loss of RASSF10 expression in kidney cancer correlated with its increasing promoter methylation." (PMID 32047266, 2020). "We found that the low RASSF10 methylation levels are favorable for kidney cancer survival (renal papillary and clear cell carcinoma)." (PMID 32047266, 2020). "Given the high RASSF10 expression in the kidney and the affected kidneys upon Rassf10 knockout, we analyzed that the RASSF10 promoter methylation in human kidney cancer." (PMID 32047266, 2020). "RASSF10 expression is decreased in various types of kidney cancer (chromophobe, papillary, and clear cell), which was verified in a further data set and each was significant compared with normal kidney tissues." (PMID 32047266, 2020). "We found that RASSF10 is epigenetically inactivated by promoter hypermethylation in 60% of kidney cancer cell lines (9/15)." (PMID 32047266, 2020). "In independent data sets, we could validate that RASSF10 inactivation clinically correlated with decreased survival and with progressed disease state of kidney cancer patients and polycystic kidney size." (PMID 32047266, 2020). "Moreover, we observed that in human kidney cancer, RASSF10 is frequently epigenetically inactivated by its CpG island promoter hypermethylation." (PMID 32047266, 2020). "Moreover, we revealed that RASSF10 is frequently epigenetically inactivated in kidney cancer, and we show the clinical potential of RASSF10 as a biomarker in different kidney diseases." (PMID 32047266, 2020). "In summary, we observed that the levels of RASSF10 expression/methylation in combination with RASSF1A expression are suitable for prognosis and diagnosis of various kidney cancer types in humans." (PMID 32047266, 2020). "In vivo analyses of RASSF10 were missing and the function of RASSF10 has not been analyzed in kidney cancer." (PMID 32047266, 2020).
lymphoma (2 papers, 2019 to 2020). A malignant (clonal) proliferation of B- lymphocytes or T- lymphocytes which involves the lymph nodes, bone marrow and/or extranodal sites. "In detail Rassf10 knockout animals mostly suffered from lymphoma, and the mean size of measurable lymph nodes increased from 86 mg for Rassf10 wt to 285 mg Rassf10+/− to 401 mg for Rassf10−/−." (PMID 32047266, 2020). "In lymphoma reduced RASSF10 expression correlated with reduced survival (mantle cell) or an earlier death of patients (B-cell)." (PMID 31817988, 2019).
Merkel cell carcinoma (2 papers, 2013 to 2019). "The RASSF10 CpG island promoter methylation was studied in 84 Merkel cell tumor samples of which 19 were methylated." (PMID 24252868, 2013). "CpG island promoter methylation was analyzed for RASSF2, RASSF5A, RASSF5C and RASSF10 in Merkel cell tumor and skin control tissue." (PMID 24252868, 2013). "The current study adds Merkel cell carcinoma to the cancer types showing RASSF10 promoter methylation." (PMID 24252868, 2013).
thymoma (2 papers, 2019 to 2020). A neoplasm arising from the epithelial cells of the thymus. "Enlarged thymus were determined by a > 2.5x weight increase above average wt thymus (47.5 ± 2.4 mg Rassf10+/+; corrected by two thymoma)." (PMID 32047266, 2020). "In thymoma RASSF10 expression was reduced with progressed tumor type and correlated with reduced survival." (PMID 31817988, 2019). "Interestingly, enlarged thymus and thymoma were found in 24% Rassf10−/− (8/33), in 46% Rassf10+/− (12/26) but only in 11% Rassf10-wt (2/18) animals, significant regarding Rassf10+/− vs. wt." (PMID 32047266, 2020).
breast tumour (1 paper, 2016). "We found that RASSF10 is highly expressed in normal breast tissue and therefore studied breast tumour samples regarding a possible tumour driving RASSF10 inactivation." (PMID 26927176, 2016). "In summary, our study shows the breast tumour specific inactivation of RASSF10 and RASSF1A due to DNA methylation of their CpG island promoters." (PMID 26927176, 2016). "We observed a significant inactivating promoter methylation of RASSF10 in primary breast tumours." (PMID 26927176, 2016). "We therefore concluded that RASSF10 could serve as an indicator of breast tumour presence by analyzing DNA promoter methylation of RASSF10 in e.g., biopsies or body fluids." (PMID 26927176, 2016). "We found a promoter methylation of RASSF10 in 17 out of 27 breast tumour samples (63%)." (PMID 26927176, 2016). "Next we analysed breast tumour and control samples by COBRA methylation analysis for the RASSF10 promoter." (PMID 26927176, 2016).
clear cell carcinoma (1 paper, 2020). "We could also show that in independent data sets RASSF10 loss correlated not only with reduced patient survival rates, but also with tumor stage/grade and was found in different kidney entities (clear cell carcinoma, papillary cell carcinoma, and chromophobe cell cancer)." (PMID 32047266, 2020). "MYC is an oncogenic downstream target of KRAS and IL6-JAK-STAT signaling and therefore we correlated the expression of MYC and RASSF10 in primary renal papillary cell carcinoma and clear cell carcinoma." (PMID 32047266, 2020).
cyst (1 paper, 2020). A sac-like closed membranous structure that may be empty or contain fluid or amorphous material. "In polycystic kidney disease, there was a correlation between reduced RASSF10 expression and an increasing cyst size, consistent with Rassf10 loss driven renal cysts in mice and the longstanding idea of polycystic kidney disease as a neoplasia in disguise." (PMID 32047266, 2020).
invasive breast carcinoma (1 paper, 2019). A carcinoma that infiltrates the breast parenchyma. "Increased methylation of RASSF10 was revealed in primary pancreatic adenocarcinoma and invasive breast carcinoma compared to normal tissue (p = 2.0 × 10−9)." (PMID 31817988, 2019).
Kidney Cyst (1 paper, 2020). Abnormal fluid filled sac within the kidney, either acquired or congenital.
kidney tumor (1 paper, 2020). "Here we achieved the discovery and validation of the RASSF10 biomarker across different kidney tumor types, which in the next steps of biomarker development will have to be followed by assay development and analytical validation, clinical utility validation, and ultimately clinical implementation." (PMID 32047266, 2020).
neuroblastoma (1 paper, 2012). Neuroblastoma (NB) is the most common solid, extracranial childhood tumor. "In the current study, we found that several of the RASSF family genes (RASSF2, RASSF4, RASSF5, RASSF6, RASSF7, and RASSF10) to various degrees were methylated in neuroblastoma cell lines and primary tumors." (PMID 22695170, 2012).
renal carcinoma (1 paper, 2020). A carcinoma arising from the epithelium of the renal parenchyma or the renal pelvis. "Our data suggest that MYC and VEGF are negatively regulated by RASSF10 and that combination of high RASSF10 and low MYC or VEGF expression is associated with a favorable prognosis for renal cancer patients." (PMID 32047266, 2020). "In renal carcinoma (papillary and clear cells) overall survival correlated with high RASSF10 expression." (PMID 32047266, 2020). "Across different renal cancer entities, we found a significant epigenetic inactivation of RASSF10." (PMID 32047266, 2020).
renal clear cell carcinoma (1 paper, 2020). "Interestingly, we found that RASSF10 expression is positively associated with increased CDH1 levels in renal clear cell carcinoma (p = 4.6 × 10−9)." (PMID 32047266, 2020). "Reduced RASSF10 expression correlated with progressed tumor stage in renal chromophobe and renal clear cell carcinoma." (PMID 32047266, 2020). "In renal clear cell carcinoma, we also detected an inverse correlation between RASSF10 and MYC expression indicating that the loss of RASSF10 is associated with MYC induction (p < 0.004)." (PMID 32047266, 2020).
renal papillary cell carcinoma (1 paper, 2020). "Low RASSF10 and high MYC or high VEGF was significantly associated with poor prognosis of renal papillary cell cancer patients and the combination of two markers had a higher impact on impaired probability of survival compared with the low RASSF10 alone." (PMID 32047266, 2020). "Primary tumors of renal clear cell and renal papillary cell carcinoma confirmed that RASSF10 methylation correlated with decreased expression in comparison with normal kidney tissue." (PMID 32047266, 2020). "Furthermore, we correlated overall survival of renal papillary cell carcinoma patients with RASSF10 and MYC or VEGF expression by Kaplan–Meier analysis." (PMID 32047266, 2020).
serous ovarian cancer (1 paper, 2021). "In the present study, we examined the methylation status of six gene promoters (BRCA1, CST6, MGMT, RASSF10, SLFN11 and USP44) in high-grade serous ovarian cancer (HGSOC)." (PMID 35008168, 2021).
thyroid tumours (1 paper, 2016). "In primary thyroid tumours with affected lymph nodes RASSF10 methylation was increased vs. those tumours from patients with unaffected lymph nodes." (PMID 26927176, 2016).
tumor (20 papers, 2009 to 2024). "Next, we tested the ability of RASSF10 to serve as a prognostic and diagnostic biomarker in independent data sets for human neoplasia across various primary samples." (PMID 32047266, 2020). "Rassf10 heterozygous animals already suffer from an overall increased disease incidence, suggesting Rassf10 is a haploinsufficient tumor suppressor, and the loss of one allele is sufficient for its loss of function and contribution to carcinogenesis." (PMID 32047266, 2020). "The tumor-suppressor RASSF10 is a member of the tumor-suppressor family Ras-Association Domain Family (RASSF)." (PMID 32047266, 2020). "We suggest that for the inactivation of the haploinsufficient tumor-suppressor RASSF10 the methylation of one allele is sufficient and found that low methylation levels of RASSF10 already decreased its expression dramatically." (PMID 32047266, 2020). "We are presenting compelling evidence that the haploinsufficient tumor-suppressor RASSF10 can be used as a prognostic and diagnostic cancer biomarker in combination with other tumor related genes (e.g., MYC) in kidney diseases." (PMID 32047266, 2020). "We assumed that loss of the tumor-suppressor RASSF10 in cancer contributes to the transition of epithelial to mesenchymal cell phenotypes." (PMID 31817988, 2019). "At last, we tested the ability of RASSF10 to serve as a prognostic and diagnostic biomarker in independent data sets for human neoplasia across various primary samples." (PMID 31817988, 2019). "Our focus lies on the tumor suppressors of the Ras-association domain family (RASSF) containing 10 members (RASSF1A to RASSF10), which are frequently inactivated via the methylation of their CpG island promoter." (PMID 25750636, 2015). "The presence of methylation of RASSF10 was associated with adverse features including lymph node metastases (P < 0.05) and increased tumor stage (P < 0.05)." (PMID 25638156, 2015). "We tested if Rassf10 loss induces spontaneous tumor formation in aging mice." (PMID 32047266, 2020). "Here, we now confirmed the prognostic and diagnostic value of RASSF10 across tumor types." (PMID 31817988, 2019). "Furthermore, we found that RASSF10, but not ASPP2, is frequently hypermethylated in human cancers and the loss of RASSF10 is associated with advanced tumor stages and impaired survival of cancer patients." (PMID 31817988, 2019). "Methylation of RASSF10 was associated with tumor size and stage." (PMID 26124922, 2015). "Methylation of RASSF10 is associated with tumor size and TNM stage, and it may serve as a docetaxel resistant marker in human HCC." (PMID 26124922, 2015). "Epigenetic regulation of RASSF10 (Ras-association domain family), a target of TGFβ, was reported to inhibit EMT by interacting with and stabilizing the ASPP2 tumor suppressor gene." (PMID 35563709, 2022). "To analyze the tumor-suppressor function of RASSF10 in an animal model, we generated the Rassf10 knockout mouse." (PMID 32047266, 2020). "In the Rassf1A−/− tumor-suppressor background, the additional Rassf10 knockout reduced significantly the overall survival (p = 0.018)." (PMID 32047266, 2020). "In our study, we generated the first Rassf10 knockout mouse model/animal model and we present Rassf10 as a novel haploinsufficient tumor suppressor in vivo." (PMID 32047266, 2020).